CASP1 (caspase 1)
Diseases named in the same sentence as CASP1 in open-access papers (continued):
Sharing a sentence is not in itself a finding about the gene and the disease.
ovarian carcinoma (16 papers, 2010 to 2026). A malignant neoplasm originating from the surface ovarian epithelium. "Recent research has shown that ovarian cancer cell death is associated with the activation of caspase-1, caspase-3, and caspase-9." (PMID 21526214, 2011). "Collectively, our findings reveal that DHA compromises ovarian cancer cell survival by triggering ROS- and caspase-1-dependent pyroptosis and mitochondrial dysfunction." (PMID 41535260, 2026). "To determine the role of caspase-1 in DHA-induced pyroptotic cell death in A2780 human ovarian cancer cells, we pretreated these cells with the specific caspase-1 inhibitor YVAD." (PMID 41535260, 2026). "We also described that these phenomena are dependent on the ovarian cancer cell oxidative status and caspase-1 activation." (PMID 41535260, 2026). "Calbay and others discovered that DHA also triggers pyroptosis in various ovarian cancer cells in vitro, in a caspase-1 dependent manner." (PMID 41535260, 2026). "We recently demonstrated that polyunsaturated fatty acids trigger a caspase-1/GSDMD-mediated pyroptosis in ovarian cancer cells in a mechanism requiring translational augmentation of caspase-1 that is independent of ASC/inflammasome." (PMID 40701951, 2025). "A previous study found that caspase 1 was abundant in the normal ovarian surface epithelium but was reduced in ovarian cancer cell lines." (PMID 36430324, 2022). "Thus, our data suggest that the effects triggered by DHA on the ovarian cancer cell A2780 are mediated by increased ROS production and caspase-1 activation." (PMID 41535260, 2026). "As an upregulated lncRNA in ovarian cancer tissues and cell lines, HOTTIP silencing leads to NLRP1 inflammasome-mediated pyroptosis, decreases cell viability, increases the expression of pro-pyroptosis factors, like IL-18, IL-1β, and NLRP1, and activates caspase-1 in ovarian cancer cells." (PMID 39967908, 2025). "Furthermore, IRF1 directly mediates the interferon-γ (IFN-γ)-induced apoptosis via the activation of caspase-1 gene expression in IFN-γ-sensitive ovarian cancer cells." (PMID 27806724, 2016). "Therefore, the downregulation of caspase 1 may be related to increased resistance to apoptosis in ovarian cancer cells." (PMID 36430324, 2022). "Finally, for a different gynaecological cancer type of human origin, human ovarian carcinoma, we could show ex vivo that infection of TAMs from ascites with S. flexneri M90TΔaroA induced caspase-1 activation and PARP cleavage." (PMID 20221397, 2010). "By screening 31 drugs with 110 targets, FNTA, HSPA5, NEU1, CCND1, CASP1, CASP3 were negatively correlated with ovarian cancer, and HMGCR, PLA2G4A, ITGAL, PTGS1, FNTB were positively correlated with ovarian cancer." (PMID 38651149, 2024). "lncRNA GAS5 prevents the progression of ovarian cancer by activating ASC, caspase 1, and IL‐1 in a time‐dependent manner to create inflammasomes and induce pyroptosis." (PMID 37752941, 2023). "Among them, FNTA, HSPA5, NEU1, CCND1, CASP1, CASP3 had a negative causal association with ovarian cancer development, and HMGCR, PLA2G4A, ITGAL, PTGS1, FNTB had a positive causal association with ovarian cancer development." (PMID 38651149, 2024). "In addition aspirin may inhibit several targets such as HSPA5, NEU1, CCND1, CASP1, CASP3, which are negatively correlated with ovarian cancer prognosis." (PMID 38651149, 2024). "Therefore, we performed methylation analysis of 51 PYAGs and showed that AIM2, CASP1, CASP8, GSDMC and NLRP6 exhibited hypomethylation in ovarian cancer, which may provide a new theory to explore the methylation of above five genes to improve potential antitumor efficacy of OC." (PMID 36707884, 2023).
acute pancreatitis (15 papers, 2013 to 2025). An acute inflammatory process that leads to necrosis of the pancreatic parenchyma. "NLRP3, ASC, and caspase-1 are involved in inflammation associated with acute pancreatitis as loss of any of these signaling components has been shown to reduce the severity of acute pancreatitis." (PMID 38585277, 2024). "It has also been shown that inhibition of caspase-1 leads to reduced acinar cell death by necrosis in severe acute pancreatitis." (PMID 38585277, 2024). "Pharmacological inhibition of caspase-1 also effectively improved renal function in rats with severe acute pancreatitis." (PMID 30670928, 2018). "Studies have found that emodin can reduce the increased expression of NLRP3, ASC, caspase-1 p10, and GSDMD proteins in alveolar macrophages induced by acute pancreatitis and improve pancreatitis-associated lung injury by inhibiting macrophage pyroptosis pathway." (PMID 38671352, 2024). "MCC950 could inhibit the expression of NLRP3 inflammasome in the pancreas of acute pancreatitis mice, as well as the expression of caspase-1 in the small intestine and down-regulate the expression of cytokines, thus alleviating pancreatic and intestinal injury." (PMID 36327405, 2022). "Lactic acid, a metabolite of bifidobacterium, can alleviate the progression of acute pancreatitis by regulating TLR 4/MyD 88 and NLRP 3/Caspase 1 pathways." (PMID 40860654, 2025). "In fact, the components of the inflammasome, ASC, caspase-1, and NLRP3, are required for the development of inflammation in acute pancreatitis." (PMID 29230270, 2017). "Moreover, in obese mice with severe acute pancreatitis, orlistat alleviated adipose tissue necrosis by inhibiting the NLRP3-caspase 1 inflammasome pathway of adipose tissue macrophages." (PMID 38468241, 2024). "CTSB may aggravate acute pancreatitis (AP) by activating the NLRP3 inflammasome and promoting caspase-1-induced pyroptosis." (PMID 36552871, 2022). "To determine whether pyroptosis is responsible for STC-induced acute pancreatitis, we detected NLRP3 (inflammasome sensor), caspase-1, and GSDMD expression by Western blotting in vivo and in vitro." (PMID 34422214, 2021). "They showed that caspase-1, ASC, and NLPR3 were necessary for inflammation in acute pancreatitis." (PMID 32076577, 2020). "Specific inhibitors targeting caspase-1/11 have been shown to effectively suppress protein expression, reduce neuroinflammatory markers, and improve survival rates, as demonstrated in studies involving acute pancreatitis, EAE, and non-canonical cell death." (PMID 41288075, 2025).
kidney damage (15 papers, 2011 to 2026). "Notably, NET-derived DAMPs, including cf-DNA, perpetuate renal inflammation by activating the TLR4/NLRP3 inflammasome axis, which triggers caspase-1-dependent cytokine maturation and establishes a self-amplifying “NETs–inflammasome–tissue injury” loop, a hallmark of progressive kidney damage." (PMID 41244813, 2025). "Sodium urate acts as a danger signal in vivo, activating the NLRP3/ASC/Caspase-1 signaling pathway, which plays a pivotal role in inflammation and kidney damage." (PMID 40005069, 2025). "Improved glycemic control and nephropathy were associated with increased circulating GLP-1, decreased renal P-38 MAPK and caspase-1 activation and reduced SGLT-2 expression." (PMID 37731032, 2023). "Inhibition of NLRP3 inflammasome activation by silencing NLRP3/ASC or repressing caspase-1 activity has been shown to decrease the production of IL-1β and alleviate kidney damage." (PMID 34504642, 2021). "Therefore, it is impossible to conclude on a role of caspase-1 and Cybb in CaOx crystal-induced nephropathy." (PMID 33968083, 2021). "In a mouse model of nephrocalcinosis, we observed that only B6N but not Casp1-, Cybb- and Casp1/Cybb-deficient mice developed CaOx crystal-induced nephropathy." (PMID 33968083, 2021). "Activation of TLR4 and the NLRP3 inflammasome promotes the maturation and release of caspase-1, along with downstream cytokines such as IL-1β and IL-18, triggering a persistent pro-inflammatory state crucial for the continued progression of hyperuricaemia nephropathy." (PMID 38041694, 2023). "Notably, we demonstrated that NLRP3 or Caspase-1 deficiency ameliorated renal tubular injury in a murine model of AAN, thus identifying renal NLRP3 inflammasome activation as a crucial mediator in the pathogenesis of AA-induced nephropathy." (PMID 31616439, 2019). "This conclusion is also supported by our human data showing CASP1 mRNA induction only in the tubulointerstitium, where most of the NLRP3 inflammasome-related genes are found to be induced in human nephropathies and where renal dendritic cells reside." (PMID 22046355, 2011). "Additionally, the lack of caspase 1 protected against the development of nephropathy in STZ-induced diabetic animals." (PMID 31540220, 2019). "In addition, the mRNA and protein expression of Caspase-1 in the LN group was significantly higher than that in SLE patients without kidney damage." (PMID 30202244, 2018). "In addition, we used inhibitors of caspase-1, NLRP3 and GSDMD-N, verifying that inhibition of the pyroptosis process could significantly mitigate proteinuria and kidney damage in PHN rats, indicating the potential for the treatment of MN with inhibitors of Caspase-1, NLRP3, and GSDMD-N." (PMID 35351877, 2022).
osteoarthritis (15 papers, 2016 to 2026). A noninflammatory degenerative joint disease occurring chiefly in older persons, characterized by degeneration of the articular cartilage, hypertrophy of bone at the margins and changes in the synovial membrane. "Caspase-1 regulations related to macrophages and lipid metabolism are another link between chondrocyte maintenance and disorders such as in the case of osteoarthritis." (PMID 34502478, 2021). "From this point of view, caspase-1 inhibition would have a protective effect related to the progression and severity of osteoarthritis." (PMID 34502478, 2021). "Assessment of the effect of dexmedetomidine on NLRP3 expression, Casp1 activation and levels of IL-1ß and mechanical allodynia in model of osteoarthritis induced by papain." (PMID 32973552, 2020). "The present study demonstrated that ICA inhibited LPS-mediated chondrocytes injury and pyroptosis and alleviated rat osteoarthritis by inhibiting NLRP3 and caspase-1 signaling." (PMID 31511005, 2019). "In osteoarthritis, moderate-intensity exercise reduces inflammation and pyroptosis by increasing the expression of Metrnl, an adipomyokine that inhibits the PI3K/Akt/NF-κB signaling pathway and subsequently the NLRP3/caspase-1/GSDMD pathway." (PMID 41399377, 2026). "The genes enriched in the osteoarthritis pathway revealed by IPA of the DEGs in the palovarotene-treated chondrocytes included various matrix catabolic genes (Adamts4, Adamts5, Mmp9, Mmp10, Mmp12, and Mmp13) and cell death-related genes (Casp1, Casp3, and Casp6)." (PMID 39062860, 2024).
Hypertension (14 papers, 2013 to 2023). The presence of chronic increased pressure in the systemic arterial system. "Since calcification is closely linked with hypertension, aging and cardiovascular mortality, it would be particularly interesting to investigate caspase-1 activation and IL-1β release from VSMCs derived from hypertensive patients." (PMID 29274344, 2018). "The putative mechanism by which hypertension in combination with overweight drives caspase-1 expression in CD16+ monocytes has to be illuminated." (PMID 33114648, 2020). "It is noteworthy that compared with young adult rats, greater renal expression of NLRP3 and caspase-1 is reported to occur in old rats and so it is plausible that inflammation-driven hypertension is augmented in old age." (PMID 28659507, 2017). "Despite having higher renal expression of Nlrp3, Casp-1 and Il-1β, Ang II-induced hypertension (SBP: 139±7 mmHg) was unaffected by co-infusion of the NLRP3 inflammasome inhibitor, MCC950 (10 mg/kg/d; SBP: 145±10 mmHg)." (PMID 28659507, 2017). "The expression of 6 out of 38 caspase-1 interaction proteins were changed in metabolic diseases; and 3 and 4 interaction proteins were upregulated in coronary heart disease and hypertension, respectively." (PMID 27842563, 2016). "Hyperhomocysteinemia, a risk factor for the development of hypertension and its complications, has been shown to induce NLRP3 inflammasome assembly, caspase-1 activation and pyroptosis in endothelial cells, while mice deficient in caspase-1 or NLRP3 are protected." (PMID 36620210, 2022). "NLRP3 activation results in caspase-1 activation and subsequent secretion of IL-1β and IL-18, the plasma levels of which are consistently high in patients with hypertension." (PMID 36620210, 2022). "Here, classic hallmarks of human PE, including hypertension, proteinuria, fetus restriction, placental oxidative damage and renal impairment, appeared in PE mice, while caspase-1 knockout could improve PE-related symptoms." (PMID 32001671, 2020). "Interestingly; T2DM patients with hypertension shows significantly decreased levels of IL-1β and caspase-1 (P value = 0.024, 0.028, resp)." (PMID 23762057, 2013). "In mice with deoxycorticosterone acetate and saline (1K/DOCA/salt)-induced hypertension, the mRNA levels of NLRP3, ASC, pro-caspase-1 and pro-IL-1β were evaluated, as well as the protein expression of active caspase-1 and mature IL-1β." (PMID 34305953, 2021). "Previous research found that activation of the NLRP3 inflammasome results in endothelial injury in hypertension, while ST inhibits the expression of NLRP3 and caspase-1, restraining the activity of the NLRP3 inflammasome." (PMID 33633569, 2020). "The results showed that ST alleviated the inflammation in hypertension, which manifested as reduced NLRP3 and caspase-1 levels, and demonstrated that ST had an inhibitory effect on the activation of the NLRP3 inflammasome." (PMID 33633569, 2020). "However, our data shows that T2DM patients with hypertension had significantly lower levels of IL-β and Caspase-1 and slightly higher levels of IL-6 and IL-10, compared to patients with no hypertension." (PMID 23762057, 2013).
parasitemia (14 papers, 2013 to 2025). "Strikingly, combined deficiency in TLR11 and Casp1/11 resulted in rapid susceptibility to parasitic infection caused by impaired T cell-derived IFN-γ responses during infection." (PMID 31194844, 2019). "In line with our results, deficiency in caspase-1 resulted in high levels of parasitemia and increased number of amastigotes within macrophages isolated from caspase-1 KO mice and infected with T. cruzi-Y strain." (PMID 29774028, 2018). "In order to evaluate the role of NLRP3 and caspase-1/11 in the control of the parasite infection in vivo, we analyzed the parasitemia and survival curves in the three mouse strains." (PMID 29774028, 2018). "We infected Aim2−/−, Nlrp3−/−, and Casp1−/− mice with YM-iRBCs, and found that parasitemias in Aim2−/−, Nlrp3−/−, and Casp1−/− mice were markedly lower than those in WT mice." (PMID 30470758, 2018). "Caspase-1 deficiency abrogated the effect of ABA on parasitemia, suggesting that caspase-1 mediated immunity is critical to the reduction in parasitemia by ABA." (PMID 29891920, 2018). "To test these inferences, we utilized passive immunization and knockout mice to demonstrate that ABA supplementation increases circulating levels of protective, parasite-specific IgG and requires caspase-1 to reduce parasitemia." (PMID 29891920, 2018). "Strikingly, caspase-1/11−/− mice showed the most dramatic reduction in the number of IFN-γ- and IL-17-producing CD4+ and CD8+ T cells associated with higher parasitemia and lower survival." (PMID 29774028, 2018). "NLRP3 and the effector protease caspase-1 appear to participate in controlling the acute phase of T. cruzi infection, as NLRP3−/− and caspase-1−/− mice exhibit a very prominent peak parasitemia, despite their ability to secrete IL-6 and IFN-γ." (PMID 24098823, 2013). "In our model, the NLRP3−/− and caspase-1−/− mice behaved in a manner identical to the iNOS−/− mice, with a higher magnitude of peak parasitemia compared to WT mice; however, most of the NLRP3−/−, caspase-1−/− and iNOS−/− mice survived infection." (PMID 24098823, 2013). "NLRP3 inflammasomes appear to control T. cruzi replication during the acute phase of infection, as NLRP3−/− and caspase-1−/− mice exhibit a very prominent peak parasitemia 11 d after infection." (PMID 24098823, 2013). "al, 2021 demonstrated that Casp1 alone is sufficient for controlling cryptosporidiosis raising the possibility that Casp1 could be sufficient for the control of other parasitic infections." (PMID 39446964, 2024). "Moreover, ST18 induced the activation, in infected macrophages, of caspase-1, a conserved enzyme that plays a major role in controlling parasitemia, host survival and the onset of the adaptive immune response in Trypanosoma infection." (PMID 34832980, 2021). "Moreover, this compound induced the activation, in infected macrophages, of caspase-1, an evolutionarily conserved enzyme that plays a major role in controlling parasitemia, host survival and the onset of the adaptive immune response in T. cruzi infection." (PMID 34832980, 2021). "The rapid susceptibility of TLR11xCasp1/11-/- mice suggests that Casp1/11 is required for strong induction of IFN-γ in the absence of TLR11 during parasite infection." (PMID 31194844, 2019). "The defect in NO production by spleen cells isolated from the NLRP3−/− and caspase-1−/− mice could explain the high levels of parasitemia observed in the iNOS−/−, NLRP3−/− and caspase-1−/− mice." (PMID 24098823, 2013). "Furthermore, the activation of the AIM2 inflammasome and caspase-1-dependent signaling negatively regulate host immune responses against lethal P. yoelii YM infection, and parasitemia is reduced in infected AIM2- and caspase-1-deficient mice compared with wild-type mice." (PMID 39548522, 2024). "In parasites infection, NLRP12 can function in inflammasome formation and was crucial for caspase-1 activation and IL-1β production during rodent malaria infection." (PMID 34956178, 2021).
parasitemia (continued). "Consistently, parasitemia and mortality in DKO mice were markedly increased, compared with those of Il1r1−/− or Casp1−/− mice." (PMID 30470758, 2018). "T. gondii infection alone did not induce caspase-1 activity, but parasite infection reduced LPS-induced caspase-1 activity, and greater than 95% of LPS-treated, infected cells were FLICA negative." (PMID 29440572, 2018). "It is noteworthy that caspase-1/11−/− group exhibited a light increase of ALT though a strong increase in AST and LDH at 21 dpi probably due to the reduced infiltrated inflammatory foci in liver but increased and disseminated parasitemia." (PMID 29774028, 2018). "Interestingly, the degree of parasitemia exhibited by the NLRP3−/− and caspase-1−/− mice was comparable to that exhibited by the MyD88−/− and iNOS−/− mice, which are considered susceptible models for T. cruzi infection." (PMID 24098823, 2013). "However, mice deficient in NLRP3 and caspase-1 are resistant to P. yoelii YM infection and present lower levels of parasitemia than wild-type mice do, indicating that NLRP3 and caspase-1 inflammasome activation negatively modulates host immune responses to resist lethal P. yoelii YM infection." (PMID 39548522, 2024). "However, other studies show that NLRP3, ASC, Caspase-1, IL-18, or IL-1 receptor have minor or no impact on parasitemia control or mouse survival." (PMID 30470758, 2018).